EGFR (epidermal growth factor receptor)
Diseases named in the same sentence as EGFR in open-access papers (continued):
Sharing a sentence is not in itself a finding about the gene and the disease.
breast carcinoma (continued). "In breast cancer cells, Notch pathway is used by cancer cells to compensate for EGFR targeted inhibition." (PMID 26497899, 2015). "Our data are consistent with a recent report that the expression of miR141 and EGFR is inversely correlated in breast cancer." (PMID 26025929, 2015). "In turn, SFKs phosphorylate EGFR on an additional tyrosine (Y845), resulting in EGFR-mediated proliferation of breast cancer cells via STAT5B." (PMID 26087188, 2015). "EGFR overexpression is also correlated with aggressive pathological features and poor outcome of breast cancer patients." (PMID 26307676, 2015). "Induction of c-Met by EGFR inhibition has also been demonstrated in breast cancer and glioblastoma multiforme." (PMID 26000702, 2015). "The targeted delivery of miRNAs by exosomes was demonstrated in a study in breast cancer cells expressing high levels of EGFR." (PMID 25338714, 2015). "In conclusion, unraveling the interaction between the critical signaling pathways in breast cancer biology including ERα, EGFR, and IGF components should provide additional new concepts in designing combination therapies." (PMID 26258011, 2015). "The increased Tyr211 phosphorylation of PCNA induced by EGFR coincides with pronounced cell proliferation and is closely correlated with the poor survival of breast cancer patients." (PMID 25675097, 2015). "Particularly, in breast cancer, anti-Her2/EGFR molecules represent the standard therapy for Her2-positive malignancies." (PMID 26181203, 2015). "The growth inhibition of the EGFR inhibitors erlotinib and lapatinib in the breast cancer MCF-7 cells was examined." (PMID 26036637, 2015). "Although 50–70% of tumors of the TNBC subtype of breast cancer express EGFR, the therapeutic efficacy of EGFR-targeting agents has been disappointing and despite cytotoxic chemotherapy, the outcome remains poor." (PMID 26313651, 2015). "The miR-124-3p was shown to be a novel tumor suppressor and a co-regulating EGFR driven cell cycle protein, inhibiting proliferation in breast cancer." (PMID 26763900, 2015). "Of note, breast cancer cells treated with the anti-ERBB2 moAb trastuzumab have an activation of EGFR signalling as a mechanism of acquired resistance." (PMID 26318427, 2015). "We wanted further to determine if PTPH1 decreases EGFR tyrosine phosphorylation in breast cancer cells." (PMID 26079946, 2015). "Ano1 has been found to activate the EGFR signaling pathway, and promotes breast cancer tumorigenesis." (PMID 25961581, 2015). "In conclusion, mutant EGFR can enhance some of the tumourigenic properties in the MCF10A/MCF10CA1a breast cancer progression model including proliferation, migration, invasion and tumour formation." (PMID 25969993, 2015). "Then, the modified exosomes can deliver the let-7a miRNA after intravenous injection to EGFR-expressing xenograft breast cancer tissue in immunodeficient mice." (PMID 25338714, 2015). "More recent work has demonstrated that EGFR inhibitors are synergistic with trastuzumab in models of HER2+ breast cancer, again suggesting that EGFR is important as an alternative pathway when HER2 is inhibited." (PMID 26121470, 2015). "Unfortunately, the therapeutic efficacy of EGFR-targeting agents has been disappointing in breast cancer, suggesting that other molecular drivers also contribute to the malignancy." (PMID 25883211, 2015). "Here we demonstrated that CH12 had a significant growth-suppression effect on EGFRvIII+HER2+ breast cancers in vitro and in vivo at least partially through inhibiting the phosphorylation of EGFR, AKT and STAT3." (PMID 26474285, 2015). "In this study, a transplantable mouse model for Wnt1/iFGFR1-driven breast cancer was employed to demonstrate changes in the stromal microenvironment and EGFR signaling occurring during tumor dormancy and recurrence." (PMID 26581390, 2015). "The level of EGFR was high in all TNBC cell lines tested compared to the luminal breast cancer cell line MCF7." (PMID 25955731, 2015).
breast carcinoma (continued). "Our results thus suggest that AMPK activating agents have potential therapeutic benefit for HER2- and EGFR-dependent breast cancers." (PMID 26143491, 2015). "Because of the crucial role of EGFR in breast cancer, several therapies that target EGFR, including gefitinib, cetuximab, lapatinib, and others, have been developed." (PMID 26025929, 2015). "The aim of our work was to identify cytosolic proteins affected by EGFR inhibition that promote caspase-8 activation in a breast cancer model." (PMID 26036637, 2015). "Gefitinib, a tyrosine kinase inhibitor, has been shown to reduce cell proliferation and tumor growth in breast cancer cell lines or in vivo conditions in xenografted animals with different levels of EGFR or HER2 expression." (PMID 26258011, 2015). "Nuclear EGFR binds to the cyclin D1 promoter region and upregulates cyclin D1 expression to promote breast cancer cell cycle progression." (PMID 25997448, 2015). "Further, EGFR copy number gain, or PTEN loss or PIK3CA mutation have been shown to promote brain metastases from breast cancer." (PMID 25969993, 2015). "A strong positive correlation was found between Anxa2 and EGFR overexpression in breast cancer tissues." (PMID 26307676, 2015). "For example, in breast cancer cell lines, Ano1 promotes breast cancer progression by activating the epidermal growth factor receptor (EGFR) and calmodulin-dependent protein kinase (CAMK) signaling pathways." (PMID 25961581, 2015). "Notwithstanding this presumption, a more recent study on breast cancer suggests that EGFR has the ability to recruit and phosphorylate IRS-1 at Y896." (PMID 25886138, 2015). "Together, CH12 significantly suppressed the growth of EGFRvIII+HER2+ breast cancers in vitro and in vivo via inhibiting EGFR downstream signals." (PMID 26474285, 2015). "Further investigation into how EGFR interacts with other oncogenic pathways will be important to aid the understanding and treatment of breast cancer." (PMID 25969993, 2015). "We also analyzed an independent study of lapatinib resistance in the BT474 breast cancer cell-line and found the same signaling pathways making cross-talks with the EGFR/ErbB signaling pathway as in the primary dataset." (PMID 25599599, 2015). "More recently, mutations in EGFR have been identified in TNBC in up to ~11% (8/70) of Asian patients, although these mutations seem much rarer in European and Australian breast cancer cases, at 1.3% (3/229) and 0% (0/50), respectively." (PMID 25969993, 2015). "A further common aberration in epithelial tumors such as breast cancer, is upregulated cell surface expression of the epidermal growth factor receptor (EGFR)." (PMID 29861415, 2015). "We identified a highly correlated co-overexpression between KLF8 and EGFR in invasive breast cancer cells and patient tumor samples." (PMID 26025929, 2015). "Combination therapy has been proven to be effective in multiple cancer types, such as PI3K and MEK inhibition in KRAS or EGFR driven cancers and mTOR and aromatase inhibition in breast cancer." (PMID 26509262, 2015). "Administration of 30 μM curcumin for 48 h induced mainly early apoptosis associated with little late apoptosis in MDA-MB-231 (ER-/PR-/HER2-/EGFR+) breast cancer cells, a model of triple negative breast cancer which is associated with poor prognosis." (PMID 26694341, 2015). "We also observed association of EGFR, FOS and IGF1 genes with EDCs, endometriosis and breast cancer." (PMID 26512648, 2015). "EMT, a pivotal cellular process that promotes metastasis initiation, is induced by the activation of EGFR signaling in breast cancer." (PMID 26307676, 2015). "EGF has been shown to inhibit the growth of EGFR-amplified MDA-468 breast cancer and A431 epidermoid carcinoma cells, which both strongly overexpress EGFR at the protein level." (PMID 26136784, 2015). "Here we describe the identification of compounds that kill breast cancer cells that overexpress EGFR or HER2." (PMID 25865227, 2015).
breast carcinoma (continued). "ErbB-2 (avian erythroblastosis oncogene B) or HER2/neu is a member of the epidermal growth factor receptor (EGFR) family and plays an important role in the pathogenesis of breast cancer." (PMID 25665066, 2015). "Consistent with our findings, kinase activity of EGFR is also important in its nuclear translocation in breast cancer cells." (PMID 25997448, 2015). "EGFR was found to be expressed at a high level in ~50% of TNBCs and in ~70% of basal-like breast cancers." (PMID 25955731, 2015). "Tunicamycin treatment produced full sized EGFR and smaller molecular EGFR in three breast cancer cell lines." (PMID 26498681, 2015). "Studies in patients with breast cancer showing a link between clinical factors and over-expression of EGFR led to the successful treatment of chemotherapy-resistant breast tumors with agents that interfere with receptor tyrosine kinases." (PMID 26697149, 2015). "Taken together, these findings demonstrate a novel KLF8 to miR141/EGFR signaling pathway potentially crucial for breast cancer malignancy." (PMID 26025929, 2015). "EGFR mutations have been identified in triple-negative breast cancers in a small study highlighting the possible application of oral EGFR tyrosine kinase inhibition therapy in selected breast cancer patients." (PMID 26630576, 2015). "Our results suggest a novel function for t-Darpp by sensitizing breast cancer cells to EGFR inhibition." (PMID 26121470, 2015). "Our results showed that PTPH1 increases breast cancer sensitivities to TKIs through disrupting the ER-EGFR interaction by catalyzing EGFR/Y1173 de-phosphorylation." (PMID 26079946, 2015). "Extensive cross talk between the IGF signaling pathway and two major growth regulators in breast cancer, namely, ER and EGFR, is detailed in numerous studies." (PMID 25874233, 2015). "Protein tyrosine phosphatase H1 (PTPH1) dephosphorylates the tyrosine kinase EGFR, disrupts its interaction with the nuclear receptor ER, and increases breast cancer sensitivity to small molecule tyrosine kinase inhibitors (TKIs)." (PMID 26079946, 2015). "The epidermal growth factor receptor (EGFR) is one of the major oncogenes identified in a variety of human malignancies including breast cancer (BC)." (PMID 26267891, 2015). "PIK3CA, epidermal growth factor receptor (EGFR), and mesenchymal-epithelial transition factor are modulated by YB-1 to promote the growth and survival of breast cancer cells." (PMID 25790262, 2015). "Interaction of EGFR with DNA protein kinase in the nucleus, on the other hand, enhances DNA damage repair and augments breast cancer cell’s resistance to cisplatin and ionizing radiation treatment." (PMID 25997448, 2015). "We assessed a panel of Her2+ breast cancer cells with respect to their relative sensitivities to treatment with Lapatinib, a small molecule inhibitor of Her2 and other epidermal growth factor receptor (EGFR) family members that is used in clinical practice." (PMID 26084280, 2015). "In summary, this work provides significant new insights into the mechanisms of breast cancer progression and opens a new gate in the study of KLF8, miR141 and EGFR in breast cancer as potential biomarkers or therapeutic targets." (PMID 26025929, 2015). "HGF has been shown to trans-activate epidermal growth factor receptor (EGFR) in PyVmT mouse mammary carcinoma cells." (PMID 25887320, 2015). "Increased EGFR gene copy number has been inconstantly (0–51 %) reported in some EGFR-positive breast cancers." (PMID 26680641, 2015). "Here, we have shown the effect of clinically used EGFR-targeted inhibitors (gefitinib and lapatinib) on the EGFR homodimerization kinetics in a basal-like breast cancer cell line, HCC1954." (PMID 25762314, 2015). "EGFR overexpression in breast cancer is correlated with large tumor size, more stem-cell like properties and poor prognosis." (PMID 25501339, 2015).
breast carcinoma (continued). "The current study, for the first time, showed that blocking EGFR signaling significantly delayed the recurrence of BGJ398-treated mammary tumors." (PMID 26581390, 2015). "Our findings showed that stromal remodeling, accompanied by upregulation of EGFR signaling, is correlated with mammary tumor recurrence, providing new insights into the development of targeted therapies." (PMID 26581390, 2015). "We identified a panel of growth factors, cytokines and chemokines potentially involved in the EGFR-mediated cross-talk between MSCs and breast cancer cells." (PMID 25344915, 2014). "Recently, a phase-specific chemotherapy resistance due to epidermal growth factor receptor (EGFR) has been demonstrated in human breast cancer cells." (PMID 24812569, 2014). "Our previous study showed that chronic treatment of triple-negative MDA-MB-231 breast cancer cells with lapatinib dramatically increased EGFR expression, which contributed to cell migration and invasion." (PMID 24707474, 2014). "Human epidermal growth factor receptor 2 (HER2), as member of EGFR superfamily, was also significantly correlated with ER-α36 expression in patients with breast cancer like EGFR." (PMID 24447535, 2014). "Estrogen sustains growth in breast cancer through the transcriptional up-regulation of various growth factors, such as EGFR, and Akt phosphorylation." (PMID 25089245, 2014). "Triple negative breast cancer (TNBC) cell lines that overexpress both EGFR and AXL appear to be more sensitive to AXL than EGFR inhibition." (PMID 25337673, 2014). "In distinction to its structural relative SAHA, TSA suppressed EGFR 3′UTR activity to attenuate its protein expression independently of HDAC inhibition in lapatinib-treated breast cancer cells." (PMID 24707474, 2014). "Cross-talk between ER and erbB2 or EGFR signaling promotes hormone-independent growth of breast cancer cells." (PMID 24886126, 2014). "EGFR overexpression is well-studied in breast cancer, and EGFR-driven signaling pathways such as PI3K/AKT/mTOR, JAK/STAT, and Ras/Raf/MAPK were associated with cell proliferation and survival." (PMID 24864132, 2014). "The ErbB2+ breast cancer cell lines used in these studies express EGFR, which has also been shown to be a target of PUVA therapy." (PMID 24551203, 2014). "Lapatinib, an orally adminstered small-molecule tyrosine kinase inhibitor targeting epidermal growth factor receptors (EGFR) and Her2/Neu, has been widely accepted in the treatment of breast cancer." (PMID 24947784, 2014). "This confirms previous findings that EGFR inhibition leads to reduced mammosphere formation in breast cancer cells when co-cultured with mesenchymal stem cells." (PMID 25361177, 2014). "Clinical data indicate that tamoxifen resistant breast cancers often have an increased expression of the receptor tyrosine kinase (RTK) epidermal growth factor (EGF) receptor (EGFR/ERBB1) and its family member ERBB2." (PMID 24758408, 2014). "Nuclear EGFR has been identified in various tumor tissues, including breast cancer, ovarian cancer, and oropharyngeal and esophageal squamous cell carcinomas, and has been shown to be associated with poor patient outcomes." (PMID 25416285, 2014). "EGFR is frequently overexpressed in many tumors, including breast cancer, and its activation contributes to unrestricted proliferation, advanced stages of disease, resistance to conventional treatments, and poor prognosis." (PMID 24629097, 2014). "It has also been demonstrated that Nicastrin stable knockdown induces Notch inhibition in basal-like breast cancer cells, sensitising them to anti-proliferative effects of EGFR inhibition." (PMID 24919951, 2014). "Recently, EGFR, mTOR, and Poly (ADP-ribose) polymerase (PARP) inhibitors were among the therapeutic agents being studied in patients with TNBC and BRCA1-associated breast cancers." (PMID 24507701, 2014).
breast carcinoma (continued). "Compensatory Notch pathway activation maintains MAPK and/or AKT downstream signaling pathways making the breast cancer cell resistant to EGFR targeted treatment." (PMID 25566499, 2014). "Using immunofluorescence (IF), we also found that CXCR7 and EGFR co-localized strongly in breast cancer tissue compared to normal breast tissue." (PMID 25168820, 2014). "Poly (ADP-ribose) polymerase (PARP), EGFR, and mTOR inhibitors are among the therapeutic agents being studied in patients with TNBC and BRCA1-associated breast cancers." (PMID 24507701, 2014). "Previous reports, included MBCs among the spectrum of basal-like breast carcinomas, since they usually display a basal/myoepithelial molecular make-up, basal-like immunophenotype, triple negativity and often show expression of EGFR, CK14 and CK5/6." (PMID 25030022, 2014). "We also found that both AG1478 and PD98059 significantly attenuated the G-1-induced growth arrest of SkBr3 cells, suggesting that inhibition effects of G-1 on ER− breast cancer cell proliferation are mediated by EGFR and sustained activation of ERK1/2." (PMID 25275589, 2014). "The most diffused currently in use are tyrosin kinase inhibitors for EGFR-mutated lung adenocarcinomas, trastuzumab for HER2-negative breast cancer and cetuximab or panituximab for KRAS-mutated CRC." (PMID 25202344, 2014). "Another strategy uses a mixture of antibodies that target EGFR (epidermal growth factor receptor), which are expressed in a subset of metaplastic breast cancer, to promote the lysosomal degradation of EGFR." (PMID 24824754, 2014). "There are several specific inhibitors of EGFR including gefitinib, erlotinib and cetuximab, and others have been studied for the treatment of breast cancer including IBC in clinical trials, but results so far remain controversial and disappointing." (PMID 24886365, 2014). "A dual, reversible EGFR/ErbB2 inhibitor, lapatinib (Tykerb) in particular has demonstrated significant activity in ErbB2-positive breast cancers and now is approved to be used in this indication." (PMID 25238247, 2014). "In estrogen receptor-positive MCF-7 breast cancer cells, overexpression of ADAM12-L promoted estrogen-independent proliferation, and this effect of ADAM12-L was linked to elevated EGFR activation." (PMID 24651654, 2014). "We further examined the effect of PI4KIIα on EGFR in two different primary isolated breast cancer cells (PIBC-1 and PIBC-2)." (PMID 24801752, 2014). "The expression levels of EGFR-GFP in MCF7-EG cells were comparable to endogenous EGFR levels in the breast-cancer derived cell line MDA-MB-468." (PMID 25062045, 2014). "The association between the variant allele (Lys) and better lymph node status appear to corroborate the notion of reduced signaling with the variant EGFR isoform, leading to lower invasiveness, which reinforce the role of EGFR in breast cancer pathogenesis." (PMID 24629097, 2014). "First line combined therapy of ER/EGFR positive breast cancer with EGFR inhibitors and tamoxifen would therefore be more effective." (PMID 24758408, 2014). "We propose that miR-7 regulated pathways, including EGFR and Src kinase, represent targets for the therapeutic intervention of refractory and metastatic HER2Δ16 driven breast cancer." (PMID 25532106, 2014). "β1 function and its cross-talk with epidermal growth factor receptor (EGFR) are crucial for the formation of invadopodia in the MDA-MB-231 breast cancer cell line cultured in both two-dimensional and three-dimensional ECM." (PMID 25606594, 2014).